MPO (myeloperoxidase)
Diseases named in the same sentence as MPO in open-access papers (continued):
Sharing a sentence is not in itself a finding about the gene and the disease.
microscopic polyangiitis (continued). "If other systemic vasculitides are suspected, the search for antibodies against the cytoplasm of neutrophilic leukocytes (ANCA) should be made, whereby there is an association between EGPA and microscopic polyangiitis (MPA) with p-ANCA (anti-MPO-ANCA) and GPA with c-ANCA (anti-PR3-ANCA)." (PMID 33324879, 2019). "Positive Perinuclear Anti-Neutrophil Cytoplasmic Antibodies (P-ANCA) and Myeloperoxidase-ANCA (MPO-ANCA) titres led to a diagnosis of microscopic polyangiitis." (PMID 30453935, 2018). "Small vessel vasculitides, such as granulomatosis with polyangiitis (GPA) and microscopic polyangiitis (MPA), are strongly associated with ANCA, which are either directed to myeloperoxidase (MPO) or proteinase 3 (PR3)." (PMID 28084533, 2017). "PR3- and MPO-ANCAs are diagnostic markers for two types of ANCA-associated vasculitis (AAV), granulomatosis with polyangiitis (GPA) and microscopic polyangiitis (MPA), respectively." (PMID 28450870, 2017). "Microscopic polyangiitis is associated with proteinase 3 (PR3)-ANCA in 26% of cases and with myeloperoxidase (MPO)-ANCA in 58% of cases, while GPA is characterized by PR3-ANCA in 66% of patients and MPO-ANCA in 24% of patients." (PMID 25452756, 2014). "Excluding atypical ANCA, perinuclear ANCA typically found in microscopic polyangiitis mainly target myeloperoxidase; by contrast, cytoplasmic ANCA against PR3 can be found in about 80% of patients with Wegener’s granulomatosis depending on disease activity." (PMID 23718545, 2013). "They reported that the titers of anti-MPO IgG4 subclass in patients with GPA was significantly higher than those with microscopic polyangiitis (MPA)." (PMID 22577389, 2012). "Myeloperoxidase (MPO)-directed ANCAs that are found in patients with Churg-Strauss disease are also found in microscopic polyangiitis." (PMID 23283308, 2008). "Microscopic polyangiitis (MPA) is a rare, necrotizing vasculitis affecting small-caliber vessels, commonly associated with anti-neutrophil cytoplasmic antibodies (ANCA), particularly anti-myeloperoxidase (MPO)." (PMID 40688904, 2025). "Granulomatosis with polyangiitis (GPA) and microscopic polyangiitis (MPA) are systemic small-vessel vasculitides, often associated with positive antineutrophil cytoplasmic antibodies (ANCA) targeting either proteinase 3 (PR3) or myeloperoxidase (MPO)." (PMID 40539188, 2025). "This retrospective monocentric study in Caen University Hospital involved all consecutive adult anti-MPO antibody-positive patients with microscopic polyangiitis or granulomatosis with polyangiitis, diagnosed between January 2010 and January 2022 with available serum sample at inclusion." (PMID 39388433, 2024). "Granulomatosis with polyangiitis typically displays a pattern of cytoplasmic ANCA (C-ANCA) almost exclusively as a result of antibodies directed against proteinase-3 (PR3), while microscopic polyangiitis typically shows a pattern of perinuclear ANCA (P-ANCA) targeting myeloperoxidase." (PMID 37375793, 2023). "The available evidence suggests an increased risk of granulomatosis with polyangiitis and proteinase 3 antibody positivity with increasing latitude and decreased UV exposure, with an inverse relationship for microscopic polyangiitis and myeloperoxidase antibody positivity." (PMID 37675201, 2023). "MPO has long been recognized as a target antigen in different forms of anti-neutrophil cytoplasmic antibody (ANCA)-associated vasculitides, microscopic polyangiitis, eosinophilic granulomatosis with polyangiitis and to a lesser frequency in granulomatosis with polyangiitis." (PMID 36421487, 2022). "Besides GPA, NCGN is also a frequent manifestation in microscopic polyangiitis (MPA), another form of ANCA-associated vasculitis (AAV) characterized by an autoimmune response against myeloperoxidase (MPO)." (PMID 33815414, 2021).
microscopic polyangiitis (continued). "This single-center, retrospective cohort study included 104 consecutive patients who were newly diagnosed with myeloperoxidase (MPO)-ANCA-positive microscopic polyangiitis (MPA) between 2006 and 2018 and were treated at the Aichi Medical University Hospital in Japan." (PMID 33301468, 2020). "The following search terms were used alone or in various combinations: “ANCA,” “proteinase 3/PR3-ANCA,” “myeloperoxidase/MPO-ANCA,” “ANCA-associated vasculitis,” “Wegener's granulomatosis,” “microscopic polyangiitis,” “Central nervous system,” “brain” and “spinal cord”." (PMID 30687221, 2018). "Here we report a unique case of MPO-ANCA microscopic polyangiitis affecting primarily the lung in a patient with a history of MPO-ANCA microscopic polyangiitis with renal-limited vasculitis and coexisting IgA deposits as well as idiopathic thrombocytopenic purpura (ITP)." (PMID 26266064, 2015). "In Japan, a high prevalence of microscopic polyangiitis (MPA) with myeloperoxidase (MPO)-ANCA among older patients has been reported; however, standard immunosuppressive therapy does not always lead to improved outcomes in this population." (PMID 42131479, 2026). "Previous studies have shown that MPO and its antibodies (MPO-ANCA) play important roles in the development of microscopic polyangiitis (MPA) and ILD." (PMID 41007698, 2025). "One hundred and thirty-six (76.0%) patients had microscopic polyangiitis (MPA), and most patients were MPO-ANCA (77.6%) and/or p-ANCA positive (60.3%)." (PMID 37853276, 2024). "Initial investigations showed elevated perinuclear anti-neutrophil cytoplasmic antibodies (P-ANCAs) and myeloperoxidase antibodies (MPOs), indicative of microscopic polyangiitis (MPA)." (PMID 39822467, 2024). "Microscopic polyangiitis (MPA) and myeloperoxidase (MPO)-ANCA have a significant predominance in Chinese AAV patients." (PMID 36244021, 2023). "ANCA and, more specifically, the enzymes myeloperoxidase (MPO) and proteinase 3 (PR3) are found in autoimmune vasculitis, which is known as ANCA-associated vasculitis and includes granulomatosis with polyangiitis, microscopic polyangiitis, and eosinophilic granulomatosis." (PMID 38283493, 2023). "First, the association of HLA-DQA1*03:02 with susceptibility to MPO-AAV and microscopic polyangiitis (MPA) and its relationship with previously reported DRB1*09:01 and DQB1*03:03 were examined in 440 Japanese patients and 779 healthy controls." (PMID 36969218, 2023). "Microscopic polyangiitis (MPA) is a systemic small-vessel vasculitis characterized by the pathogenic autoantibody, antineutrophil cytoplasmic antibody (ANCA) that reacts with myeloperoxidase (MPO)." (PMID 37932784, 2023). "In this view, when considering GPA and microscopic polyangiitis (MPA), genetic associations are stronger with ANCA specificity (PR3- or MPO-ANCA) than with the clinical diagnosis." (PMID 36719484, 2023). "The systemic autoimmune diseases granulomatosis with polyangiitis and microscopic polyangiitis are small vessel vasculitis syndromes associated with circulating antineutrophil cytoplasmic antibodies (ANCA), which target either proteinase 3 (PR3) or myeloperoxidase (MPO)." (PMID 34618687, 2021). "MPO-ANCA is detected predominantly in patients with ANCA-associated vasculitides, such as microscopic polyangiitis (MPA), granulomatosis with polyangiitis (GPA), and eosinophilic granulomatosis with polyangiitis (EGPA)." (PMID 29928060, 2018). "Anti-myeloperoxidase (MPO) positivity is uncommon in GPA and often creates clinical overlap with microscopic polyangiitis." (PMID 41798537, 2026). "Serology confirmed myeloperoxidase (MPO)-ANCA positivity, supporting a diagnosis of AAV, most consistent with microscopic polyangiitis." (PMID 42245628, 2026). "This cohort included 33 patients with granulomatosis with polyangiitis (GPA), all positive for PR3-ANCA, and 94 with microscopic polyangiitis (MPA), of whom 90% were positive for MPO-ANCA." (PMID 39797292, 2025).
microscopic polyangiitis (continued). "AAV is divided into three distinct clinical-pathological phenotypes including granulomatosis with polyangiitis (GPA), microscopic polyangiitis (MPA) and eosinophilic granulomatosis with polyangiitis (EGPA), and are associated with proteinase 3 (PR3) and myeloperoxidase (MPO) antibodies." (PMID 40907826, 2025). "This group includes Microscopic Polyangiitis (MPA), Eosinophilic Granulomatosis with Polyangiitis (EGPA), both associated with p-ANCA and anti-MPO positivity, and Granulomatosis with Polyangiitis (GPA), which is associated with the presence of c-ANCA and anti-PR3." (PMID 40282891, 2025). "ILD is a common complication of AAV, especially myeloperoxidase (MPO)-ANCA-positive AAV and microscopic polyangiitis (MPA)." (PMID 39305386, 2024). "Three patients were microscopic polyangiitis (MPA) myeloperoxidase (MPO)-ANCA positive." (PMID 38833076, 2024). "In the MPO-ANCA positive group, 2 patients were presumed to have coexisting IgG4-RD and microscopic polyangiitis." (PMID 37670401, 2023). "Among AAV patients, 61 (98.4%) were positive for MPO- or P-ANCA and were diagnosed as having microscopic polyangiitis." (PMID 38111574, 2023). "AAV can be divided into granulomatosis with polyangiitis (GPA), microscopic polyangiitis (MPA), and eosinophilic GPA (EGPA) based on clinical phenotype, or PR3-ANCA disease vs MPO-ANCA disease based on ANCA specificity." (PMID 36942002, 2023). "Lung involvement is frequent in AAV, and interstitial lung diseases (ILDs) are strongly related to MPO-ANCA positivity and mainly reported in microscopic polyangiitis." (PMID 35207604, 2022). "That is, whether classification should be based on the serotype (proteinase 3 (PR3)- or myeloperoxidase (MPO)-ANCA) or on the clinical phenotype (granulomatosis with polyangiitis (GPA) or microscopic polyangiitis (MPA))." (PMID 33909191, 2021). "Myeloperoxidase antineutrophil cytoplasmic antibody (MPO-ANCA) is often positive in patients with interstitial lung disease (ILD), which is also often present in patients with microscopic polyangiitis (MPA)." (PMID 34732182, 2021). "Microscopic polyangiitis (MPA) and myeloperoxidase (MPO)-ANCA positive AAV (MPO-AAV) are predominant in East Asian populations, while granulomatosis with polyangiitis (GPA) and proteinase 3 (PR3)-ANCA positive AAV (PR3-AAV) are common in the populations of European ancestry." (PMID 33076992, 2020). "Additionally, given the presence of the myeloperoxidase antibody and glomerulonephritis on renal biopsy, our patient was diagnosed with microscopic polyangiitis (MPA)." (PMID 30131924, 2018). "The most compelling human evidence relates to reports of a neonate who developed pulmonary renal syndrome soon after birth from the trans-placental transfer of IgG MPO-ANCA from the mother, who had active microscopic polyangiitis (MPA)." (PMID 28785984, 2018). "Pre-existing chronic interstitial pneumonia might be a trigger for the production of MPO-ANCA because MPO-ANCA is known to be positive prior to the development of microscopic polyangiitis (MPA)." (PMID 28403904, 2017). "We present a case of a male patient with chronic renal insufficiency, due to crescentic glomerulonephritis with IgA deposits, who successively developed (idiopathic) thrombocytopenic purpura (ITP) and MPO-ANCA microscopic polyangiitis (MPA) with pulmonary fibrosis." (PMID 26266064, 2015). "Although microscopic polyangiitis (MPA) could be also characterized by pANCA with MPO specificity, it rarely shows peripheral eosinophilia, nodules, or eosinophilic pulmonary infiltrates." (PMID 25404930, 2014). "This group of systemic vasculitis includes granulomatosis with polyangiitis (GPA), primarily associated with antibodies to PR3–ANCA and microscopic polyangiitis (MPA) and eosinophilic granulomatosis with polyangiitis (EGPA), both principally associated with antibodies to MPO–ANCA." (PMID 25352848, 2014).
microscopic polyangiitis (continued). "The population in this trial is significantly different from those in other studies, most obviously in the proportion of patients with MPO-ANCA and microscopic polyangiitis at 87%." (PMID 20573267, 2010). "In contrast microscopic polyangiitis exhibits cANCA with PR3 specificity in approximately 30% of patients and pANCA with MPO specificity in 60% of patients." (PMID 18718013, 2008). "Antineutrophil cytoplasmic antibodies (ANCA) specific for proteinase 3 (PR3) and myeloperoxidase (MPO) are associated with necrotizing vasculitides, especially Wegener's granulomatosis (WG), microscopic polyangiitis (MPA) and idiopathic crescentic glomerulonephritis." (PMID 16207324, 2005). "This multicentre, retrospective cohort study analysed data from a nationwide Japanese registry of 729 newly diagnosed patients with granulomatosis with polyangiitis (GPA) or microscopic polyangiitis (MPA), all positive for myeloperoxidase (MPO)- or proteinase 3 (PR3)-ANCA." (PMID 41222744, 2025). "Rapid progression of coronary involvement was evidenced, along with increased markers of inflammatory response, usual interstitial pneumonia on tomography, and positive anti-myeloperoxidase antibodies (anti-MPO), leading to the diagnosis of microscopic polyangiitis (MPA)." (PMID 38596604, 2024). "Microscopic polyangiitis (MPA) is a type of AAV marked by renal involvement, which often leads to rapidly progressive glomerulonephritis and the presence of myeloperoxidase-ANCA (MPO-ANCA; although proteinase 3 (PR3)-ANCA has also been reported)." (PMID 36938279, 2023). "In contrast, stimulation of human monocytes and neutrophils with monoclonal antibodies to PR3 or myeloperoxidase (MPO, the main autoantigen of microscopic polyangiitis, another AAV) or with human ANCA IgG, led to IL-1β generation and release in an inflammasome-independent manner." (PMID 36275673, 2022). "MPO/ANCA-positive EGPA has a significant association with HLA class II DQ haplotype, which is shared with the other MPO-AAV (i.e., microscopic polyangiitis, MPA), while ANCA-negativity is associated with GP33 and IL5/IRF1 loci, indicating a possible mucosal/barrier dysfunction origin." (PMID 33718405, 2021). "Anti-neutrophil cytoplasmic autoantibodies (ANCA) are found in primary vasculitic syndromes, granulomatosis and polyangiitis (GPA) and microscopic polyangiitis (MPA) exhibit specificity for azurophilic granular proteins proteinase 3 (PR3) and myeloperoxidase (MPO)." (PMID 34142075, 2021). "It has three main clinical types, granulomatous with polyangiitis (GPA), microscopic polyangiitis (MPA) and eosinophilic granulomatous polyangiitis (EGPA), in which serum markers include protease 3 (PR3) and myeloperoxidase (MPO) that are released under the stimulation of pathogens." (PMID 33083841, 2020). "According to the CHCC classification, 55 had microscopic polyangiitis (MPA), 5 had granulomatosis with polyangiitis (GPA), 1 had eosinophilic granulomatosis with polyangiitis (EGPA), and all were positive for myeloperoxidase-ANCA (MPO-ANCA)." (PMID 31725735, 2019). "Our patient meets the criteria for microscopic polyangiitis based on the European Medicines Agency algorithm as she presented with glomerulonephritis and positive myeloperoxidase without surrogate markers for granulomatosis with polyangiitis." (PMID 27872779, 2016). "Further immunological evaluation revealed perinuclear antineutrophil cytoplasmic antibody (p‐ANCA) with anti‐myeloperoxidase (MPO) specificity, establishing a diagnosis of microscopic polyangiitis (MPA) complicated by diffuse alveolar hemorrhage (DAH)." (PMID 41403984, 2025). "Of patients with granulomatosis with polyangiitis (GPA) and microscopic polyangiitis (MPA), 85–90% have ANCA, namely anti-myeloperoxidase (MPO) or PR3 antibodies." (PMID 39661284, 2025).
microscopic polyangiitis (continued). "Granulomatosis with polyangiitis (GPA), also referred to as Wegener's granulomatosis, microscopic polyangiitis (MPA), and eosinophilic GPA (EGPA), commonly known as Churg-Strauss syndrome, are characterized by a lack of tolerance to neutrophil granule proteins like PR3 or MPO." (PMID 39439652, 2024). "This is a retrospective cohort study on myeloperoxidase (MPO)-ANCA or proteinase 3 (PR3)-ANCA positive patients with AAV (microscopic polyangiitis, MPA; or granulomatosis with polyangiitis, GPA) and eGFR <15 ml/min per 1.73 m2 or ESKD at presentation." (PMID 38707835, 2024). "Among AAV subtypes, the frequencies of ILD were significantly higher in both patients with microscopic polyangiitis (MPA) and those with AAV having myeloperoxidase (MPO)-ANCA (or P-ANCA) compared to other subtypes." (PMID 35655922, 2022). "Eosinophilic granulomatosis with polyangiitis (EGPA), Granulomatosis with polyangiitis (GPA), and microscopic polyangiitis (MPA), are the major categories of AAV, and proteinase 3 (PR3) and myeloperoxidase (MPO) are two major antigens of ANCA2." (PMID 33664381, 2021). "Microscopic polyangiitis (MPA) is an autoimmune small-vessel vasculitis often positive for perinuclear anti-neutrophil cytoplasmic antibody (p-ANCA), or anti-myeloperoxidase (MPO), that classically affects the lungs, kidneys, and skin." (PMID 33903832, 2021). "A renal biopsy revealed glomerulonephritis with pauci-immune crescents, and serology tests were positive for anti-MPO p-ANCA, both suggesting a diagnosis of microscopic polyangiitis (MPA)." (PMID 32185342, 2019). "Microscopic polyangiitis (MPA) presents with non-granulomatous inflammation with few or no immune deposits in the walls of the affected vessels, mainly associated with antibodies against MPO." (PMID 31105641, 2019). "GPA is typically associated with proteinase 3 (PR3) epitopes, while other entities like microscopic polyangiitis (MPA) and eosinophilic granulomatosis with polyangiitis (EGPA) are linked to myeloperoxidase (MPO)-ANCA or negative ANCA." (PMID 40095487, 2025). "However, limited data regarding MPO-ANCA, which has primarily been studied in microscopic polyangiitis (MPA) and eosinophilic granulomatosis with polyangiitis (EGPA), is less clear." (PMID 40959075, 2025). "Typically, c-ANCA targets proteinase 3 (PR3) and is predominant in granulomatosis with polyangiitis (GPA), while p-ANCA targets myeloperoxidase (MPO) and is more common in microscopic polyangiitis (MPA), though these associations are not absolute." (PMID 39456878, 2024). "PR3 and MPO are the predominant antigens of interest in small-vessel vasculitis and autoantibodies (ANCA) to these aid with classification of AAV subtypes granulomatosis with polyangiitis (GPA) and microscopic polyangiitis (MPA)." (PMID 38612581, 2024). "AAV includes microscopic polyangiitis (MPA), granulomatosis with polyangiitis (GPA), eosinophilic granulomatosis with polyangiitis (EGPA), renal-limited AAV, and certain drug-induced vasculitis syndromes which may be ANCA specific for either myeloperoxidase (MPO-ANCA) or proteinase 3 (PR3-ANCA)." (PMID 35759125, 2022). "Although PR3-ANCA is known as a disease marker for GPA and myeloperoxidase (MPO)-ANCA is known as a marker for microscopic polyangiitis (MPA) or eosinophilic granulomatosis with polyangiitis (EGPA), the transfer of antibodies has been observed within AAV, and MPO-ANCA positive GPA has been reported." (PMID 26223225, 2015). "Eight years before presentation at our hospital, at age 63, she was clinically diagnosed with microscopic polyangiitis (MPA) based on rapidly progressive glomerulonephritis, mononeuropathy multiplex, positive MPO-ANCA, and negative proteinase 3–ANCA; no renal biopsy was conducted at that time." (PMID 40750159, 2025).
microscopic polyangiitis (continued). "Accordingly, MPO‐ANCA‐positive interstitial pneumonia may include not only microscopic polyangiitis and unclassified AAV but also MPO‐ANCA‐positive interstitial pneumonia without systemic vasculitis manifestations, as well as pulmonary‐limited AAV preceding the onset of AAV." (PMID 40070290, 2025).